PMS2 (PMS1 homolog 2, mismatch repair system component)
Diseases named in the same sentence as PMS2 in open-access papers (continued):
Sharing a sentence is not in itself a finding about the gene and the disease.
cancer (continued). "However, all our patients with MLH1-/PMS2-/MSH6- cancers were over 60 years of age at time of diagnosis and did not have a familiar history suspicious for cancer predisposing syndromes." (PMID 36387226, 2022). "MSH6 and PMS2 carriers developed no cancers before 40 years of age." (PMID 27606285, 2016). "On the other hand, IHC of cancer spheroid cells of two independent spheroid clones demonstrated contradictory results; one MMR-proficient with all four MMR proteins, and the other without MLH1 and PMS2." (PMID 30680068, 2018).
adenocarcinoma (19 papers, 2012 to 2026). A common cancer characterized by the presence of malignant glandular cells. "Three of the markers: GPR56, LY6G6D/F and SLCO1B3 had significantly higher expression in proximal adenocarcinomas and were positively correlated with mismatch repair protein expression, i.e. PMS2 and MSH6 with all three, and PMS1 with LY6G6D/F." (PMID 26894861, 2016). "Furthermore, in adenocarcinoma specimens from patients, those with reduced PMS2 expression had lower apoptotic ability in nearby tissue samples." (PMID 26036629, 2015). "The two tumors with MSI without expression of Rad51C variants were low grade, moderately differentiated adenocarcinoma, and had absence of MLH1 and PMS2 protein expression." (PMID 25669972, 2015). "In our patient, the immunohistochemical profile of the MMR proteins was consistent with microsatellite stability in both the DALM and the first adenocarcinoma, whereas both MLH1 expression and PMS2 expression were negative in the subsequent two tumors." (PMID 29915171, 2018).
genetic disorders (6 papers, 2016 to 2025).
gastro-intestinal tumours (4 papers, 2008 to 2025). "These are consistent with a role for Mlh3;Pms2 combined loss both to increase GI tumor initiation and accelerates progression." (PMID 18551179, 2008). "To understand more precisely the mechanistic roles that Mlh3 and Pms2 play in GI tumor suppression, we generated Mlh3−/−;Apc1638N (MA) and Mlh3−/−;Pms2−/−;Apc1638N (MPA) mice." (PMID 18551179, 2008).
hematological malignancies (4 papers, 2022 to 2025). "In addition to the genes known to predispose to hematological malignancies, patients harbored several interesting variants in genes primarily associated with an increased risk for solid tumors (MUTYH, PMS2, and CHEK2)." (PMID 35739278, 2022).
CNS tumors (2 papers, 2021 to 2024).
digestive system cancer (2 papers, 2021 to 2022). A primary or metastatic malignant neoplasm involving any part of the digestive system. "Further studies performing CNV analysis as well as whole exome or even whole genome sequencing of MLH1-/PMS2-/MSH6- digestive system cancers are necessary to fully understand the mutational landscape of these cases." (PMID 36387226, 2022). "Detailed overview and significance of MMR/HRR variants observed in MLH1-/PMS2-/MSH6- digestive system cancer cases." (PMID 36387226, 2022). "Genetic content of identified variants regarding mononucleotide repeats in MLH1-/PMS2-/MSH6- digestive system cancer cases." (PMID 36387226, 2022). "The additional MMR/HRR mutations we could detect in our MLH1-/PMS2-/MSH6- cases could play a mechanistic role in the loss of MSH6 expression in already MLH1/PMS2-deficient digestive system cancers by paving the way for further mutations in the MSH6 gene." (PMID 36387226, 2022). "If further studies with larger cohorts can prove the clustering of mutations in DNA-repair related genes in MLH1-/PMS2-/MSH6- digestive system cancers, this peculiar immunophenotype could immediately trigger additional NGS-testing for HRR mutations as basis for therapy." (PMID 36387226, 2022). "MMR immunoexpression and molecular characterization of MLH1-/PMS2-/MSH6- digestive system cancer cases." (PMID 36387226, 2022). "To the best of our knowledge, we are the first group to specifically focus on the abnormalities in DNA repair of MLH1-/PMS2-/MSH6- digestive system cancer cases." (PMID 36387226, 2022). "Clinicopathological features MLH1-/PMS2-/MSH6- digestive system cancer cases." (PMID 36387226, 2022). "Of course, our findings are limited by the rarity of MLH1-/PMS2-/MSH6- digestive system cancers." (PMID 36387226, 2022).
infection (2 papers, 2020 to 2024). The state of being infected such as from the introduction of a foreign agent such as serum, vaccine, antigenic substance or organism. "We further overexpressed PMS2 in PC9 cell lines by lentiviral infection system." (PMID 38714954, 2024).
autosomal recessive inherited disease (1 paper, 2022).
PMS2 also shares sentences with these, for which no sentence is quoted: Li-Fraumeni syndrome (8 papers); Cowden syndrome (6); juvenile polyposis syndrome (6); Peutz-Jeghers syndrome (6); polyposis (6); breast (4); Hereditary Breast and Ovarian Cancer syndrome (4); astrocytoma (3); autosomal dominant inherited disorder (3); Hereditary Pancreatitis (3); mismatch repair cancer syndrome (3); mutyh-associated polyposis (3); neurofibromatosis type 1 (3); Wilms tumor (3); ampullary cancer (2); Ataxia (2); atypical endometrial hyperplasia (2); brain cancer (2); carcinosarcoma (2); clear cell renal cell carcinoma (2); duodenal adenocarcinoma (2); hepatocellular carcinoma (2); Hereditary Diffuse Gastric Cancer (2); Immunodeficiency (2); meningioma (2); mesothelioma (2); neuroblastoma (2); Obesity (2); pheochromocytoma (2); retinoblastoma (2).
A further 99 diseases each share a sentence with PMS2 in 2 papers or fewer.